FCGR3A (Fc gamma receptor IIIa)
Diseases named in the same sentence as FCGR3A in open-access papers (continued):
Sharing a sentence is not in itself a finding about the gene and the disease.
autoimmune disease (18 papers, 2007 to 2025). A disorder resulting from loss of function or tissue destruction of an organ or multiple organs, arising from humoral or cellular immune responses of the individual to their own tissue constituents. "By combining findings from different populations, the analysis reduces the impact of insufficient statistical power in any one investigation and allows for a broader perspective on the role of FCGR3A in autoimmune disease susceptibility." (PMID 41000382, 2025). "The association between FCGR3A rs396991 and susceptibility to several autoimmune diseases was confirmed in an analysis of the European population, but further studies with greater statistical power are needed to confirm these results." (PMID 41000382, 2025). "There have also been two intergenic SNPs identified (rs2099684 and rs10919543) between FCGR2A and FCGR3A that have been associated with the autoimmune disease Takayasu arteritis in Turkish, North American and Chinese Han populations." (PMID 39345014, 2024). "The aim of this systematic review with meta-analysis was to examine the association between the polymorphisms rs1801274 (FCGR2A H131R) and rs396991 (FCGR3A F158V) and susceptibility to autoimmune diseases (ADs), with a focus on the progress and novelty of studies published over the last two decades." (PMID 41000382, 2025). "Additionally, the results suggest that both the FCGR2A (rs1801274) and FCGR3A (rs396991) polymorphisms may be associated with susceptibility to various autoimmune diseases in both European and East Asian populations." (PMID 41000382, 2025). "Thus, our results indicate that FCGR2A/FCGR3A might be a susceptibility gene for TA in patients from the Chinese Han population, suggesting that TA might share associated genetic loci with other autoimmune diseases." (PMID 27769046, 2017). "The activating Fc receptor FCGR3A is mainly expressed in NK cells and macrophages and plays an important role in autoimmune disease." (PMID 32500465, 2020). "Copy number of the genes FCGR3A and FCGR3B has previously been reported to affect susceptibility to several autoimmune diseases and chronic inflammatory conditions." (PMID 25594501, 2015). "The presence of rare variants in these genes might play a crucial role in the development of the autoimmune diseases due to their complex interactions in key related pathways regulating receptor binding and FCGR3A-mediated IL10 synthesis, which is an important immunoregulatory cytokine." (PMID 35783297, 2022). "In the studies of genetic predisposition to develop autoimmune disorders, CNV was proven only for FCGR2C, FCGR3A and FCGR3B, but not for FCGR2A and FCGR2B genes." (PMID 28472129, 2017).
melanoma (16 papers, 2010 to 2025). A malignant, usually aggressive tumor composed of atypical, neoplastic melanocytes. "Concordantly, a V158F single nucleotide polymorphism (SNP) (rs396991) of FCGR3A (encoding FcγRIIIA) was associated with improved ORR and OS in ipilimumab‐treated melanoma cohorts, specifically for those tumours with higher insertion–deletion (indel) burden." (PMID 35394069, 2022). "In this study, two populations of NK cells were identified: NKCyto (which compared with NK cells from OT metastatic melanoma lesions from NRs, expressing GNLY, CXC3R1, and FCGR3A) and NKRest (expressing XCL1 and XCL2)." (PMID 40530504, 2025). "Additionally, our study identified genes without reported expression in CMM and nevi or biological function related to melanoma progression, including CCL3L3, NPY1R, IL11A, FCGR1B, OAS2, ASB11, FCGR3A, and GLA." (PMID 35008167, 2021). "Yervoy, the first anti-CTLA-4 antibody, can deplete regulatory T cells by engaging ex vivo Fc gamma receptor IIIA-expressing, non-classical monocytes in melanoma patients." (PMID 32793247, 2018).
malaria (12 papers, 2010 to 2024). Malaria is a serious and sometimes fatal disease caused by a parasite that commonly infects a certain type of mosquito which feeds on humans. "FCGR2B is known to be a resistance factor to malaria and FCGR3A is involved in autosomal recessive immunodeficiency." (PMID 38409353, 2024). "This study focused on three SNPs in the FcγRs gene cluster that are yet to be studied in relation to malaria: two intronic SNPs (FCGR2C-rs3933769 and FCGR3A-rs396991) and a functional SNP in the FCGR2B-rs1050519." (PMID 26785902, 2016).
dengue (11 papers, 2014 to 2025). "Single-cell transcriptomics demonstrated a progressive increase in intermediate monocytes (CD14++/FCGR3A+) across clinical severity groups, peaking in severe Dengue." (PMID 41012666, 2025).
colorectal cancer (10 papers, 2011 to 2024). A primary or metastatic malignant neoplasm that affects the colon or rectum. "FCGR3A is related to treatment and metastasis in colorectal cancer (CRC)." (PMID 35360863, 2022). "We analyzed the influence of 8 germinal polymorphisms of candidate genes potentially related to EGFR signalling (EGFR, EGF, CCND1) or antibody-directed cell cytotoxicity (FCGR2A and FCGR3A) on outcome of colorectal cancer (CRC) patients receiving cetuximab-based therapy." (PMID 22117530, 2011).
follicular lymphoma (8 papers, 2013 to 2022). Follicular lymphoma is a form of non-Hodgkin lymphoma characterized by a proliferation of B cells whose nodular structure of follicular architecture is preserved. "In a study of 87 patients with follicular lymphoma who had been treated with rituximab, FCGR3A 158 V/V patients also showed a higher response rate to rituximab treatment." (PMID 23286345, 2013). "The recent PRIMA study reported that FCGR2A and FCGR3A polymorphisms do not influence the response rate and outcome of follicular lymphoma patients treated with rituximab, either when it is combined with chemotherapy or used as maintenance treatment." (PMID 23286345, 2013).
HIV-1 infection (8 papers, 2013 to 2023). The type species of lentivirus and the etiologic agent of acquired immunodeficiency syndrome (AIDS). "Here again, we evaluated potential associations between FCGR2A and FCGR3A variants and susceptibility to HIV-1 infection by accessing the results of a previous GWAS of HIV-1 acquisition that compared 6,300 HIV-1 infected individuals and 7,200 controls of European ancestry." (PMID 31143176, 2019).
metastatic colorectal cancer (8 papers, 2013 to 2021). "Most studies have been limited by small samples sizes and have reported inconsistent associations between the FCGR2A and the FCGR3A polymorphisms and clinical outcome in metastatic colorectal cancer (mCRC) patients treated with cetuximab." (PMID 24884501, 2014). "However, it provides further insight into the mechanistic role of FCGR polymorphisms in clinical outcomes of cetuximab‐treated, metastatic colorectal cancer, namely, the role of FCGR3A polymorphism in modifying the primary relationship between FCGR2A and clinical outcomes." (PMID 30318772, 2018). "In contrast, a study in metastatic colorectal cancer patients treated with cetuximab found that FCGR3A 158 V/V patients had a shorter PFS compared with 158 V/F or F/F patients." (PMID 23286345, 2013). "Cetuximab, Immunoglobulin, Rituxan and Thymoglobulin are immune-related drugs encoded by FCGR3A and CD4 genes in which Cetuximab is an epidermal growth factor receptor (EGFR) inhibitor used for the treatment of metastatic colorectal cancer and head and neck cancer." (PMID 24564241, 2013).
ovarian carcinoma (8 papers, 2020 to 2023). A malignant neoplasm originating from the surface ovarian epithelium. "Siglec-9, the receptor of MUC16, had strong correlations with markers of neutrophil ITGAM, ITGB2, FCGR1A, FCGR2A, FCGR3A, analyzed with TCGA-OV database and ovarian cancer tissue RNA sequencing data." (PMID 37644468, 2023). "Through further analysis of these key genes and cancer stem cell subpopulation, more critical genes can be obtained as LCP2, FCGR3A, COL1A1, COL1A2, MT-CYB, CCT5, and PAPPA, are closely associated with ovarian cancer." (PMID 35360863, 2022). "Through the analysis of stemness-related key genes and tumor stem cell subpopulations, LCP2, FCGR3A, COL1A1, COL1A2, MT-CYB, CCT5, and PAPPA are closely related to ovarian cancer." (PMID 35360863, 2022). "In our new analytical process, the key genes related to ovarian cancer are identified as LCP2, FCGR3A, COL1A1, COL1A2, MT-CYB, CCT5, and PAPPA, which may have important significance in ovarian cancaer and drug therapy." (PMID 35360863, 2022).
glioma (7 papers, 2018 to 2024). A benign or malignant brain and spinal cord tumor that arises from glial cells (astrocytes, oligodendrocytes, ependymal cells). "Among the three transcriptional subtypes of glioma, the mesenchymal subtype tumors have the highest expression level of FCGR3A and FGL2 as compared with classical or proneural subtypes." (PMID 39629005, 2024). "The role of FCGR3A in cancer has recently gained significant interest, with studies proposing it as a poor prognostic biomarker in prostate cancer and lower-grade glioma." (PMID 39199652, 2024). "In conclusion, our current study indicated that overexpression of FCGR3A and FGL2 is associated with poor prognosis in primary and recurrent glioma patients, especially in LGG." (PMID 39629005, 2024). "First, the transcription expression level of FCGR3A/FGL2 among glioma patients were investigated." (PMID 39629005, 2024). "Additionally, tissue microarrays from glioma patients at Tiantan Hospital showed significantly higher FCGR3A protein expression in high-grade gliomas compared to low-grade gliomas." (PMID 39629005, 2024). "The increased expression of FCGR3A and FGL2 is associated with various clinical features in glioma." (PMID 39629005, 2024). "MRNA expressions of FCGR3A and FGL2 were significantly upregulated in Low-grade gliomas and glioblastomas respectively compared to normal brain tissue, and there are few mutations in either 2 genes." (PMID 39629005, 2024). "The results of Cox regression analysis further demonstrate the independent prognostic significance of FCGR3A and FGL2 in glioma." (PMID 39629005, 2024). "Overexpression of FCGR3A and FGL2 is regarded as independent prognostic factors for shorter OS of glioma patients through Cox regression analysis." (PMID 39629005, 2024). "Given that the expression levels of FCGR3A and FGL2 exhibit similar trends across different subtypes of gliomas and the anatomical localization is the same in tumor, we propose that FCGR3A and FGL2 co express on a type of cell within gliomas." (PMID 39629005, 2024). "It shows that the high expression of FCGR3A and FGL2 in glioma is induced by tumor cells or immune cells infiltrated into the brain." (PMID 39629005, 2024). "Cox regression analysis further confirmed that elevated expression of FCGR3A and FGL2 were independent prognostic factors for shorter overall survival in glioma patients." (PMID 39629005, 2024). "The mass spectrometry results show that the abundance of FCGR3A and FGL2 proteins were also upregulated in glioma tissues in the CPTAC database." (PMID 39629005, 2024). "FCGR3A and FGL2 transcriptional expressions are found significantly higher in glioma compared with normal brain." (PMID 39629005, 2024). "Despite the growing interest in FCGR3A and FGL2 effect in glioma, their clinicopathological significance and prognostic value have received less attention." (PMID 39629005, 2024). "CLIC4 expression levels were positively correlated with specific markers of macrophages (CD80, CD86, MRC1), neutrophils (FCGR3A, FCGR3B), eosinophils (SIGLEC8, IL3RA), T cells (CD3D, CD4), CD8+ T cells (CD8A, CD8D), NK cells (NCAM1), and B cells (CD19) in glioma." (PMID 39595145, 2024). "In conclusion, our findings suggest that FCGR3A and FGL2 could serve as promising prognostic biomarkers and potential therapeutic targets for glioma patients." (PMID 39629005, 2024). "FCGR3A is significantly positively correlated with FGL2 expression in all tumor types (R=0.43), while the correlation between FCGR3A and FGL2 is more prominent in glioma samples (R=0.79)." (PMID 39629005, 2024). "This study could provide deeper insights into the prognostic value of FCGR3A and FGL2 expression in glioma, potentially leading to improved patient stratification and treatment strategies." (PMID 39629005, 2024).
glioma (continued). "Given that the expression levels of FCGR3A and FGL2 exhibit similar trends across different subtypes of gliomas and the anatomical localization is the same in tumor, we propose that FCGR3A and FGL2 co express in gliomas." (PMID 39629005, 2024).
influenza (7 papers, 2014 to 2023). An acute viral infection of the respiratory tract, occurring in isolated cases, in epidemics, or in pandemics; it is caused by serologically different strains of viruses (influenzaviruses) designated A, B, and C, has a 3-day incubation period, and usually lasts for 3 to 10 days. "Taken together, these results suggest that H3- and NA-specific antibodies with the capacity to engage FCGR3A and activate NK cells are associated with lower susceptibility to influenza following vaccination in older adults and mice." (PMID 37620306, 2023).
lung carcinoma (7 papers, 2022 to 2026). "In contrast, normal lung tissue showed strong FCGR3A staining and lung cancer showed weak FCGR3A staining." (PMID 35668930, 2022). "Furthermore, 2 risk groups of patients with lung cancer, characterized by different prognoses and immune landscapes, were stratified using a risk scoring model that comprised 3 AS-related genes (CD52, FABP5, and FCGR3A)." (PMID 41731774, 2026). "Effector CD8+ T cells express high levels of cytotoxic genes, including TBX21, KLF3, FCGR3A, KLRG1, and KLRB1, and exert cytotoxic activity in patients with lung cancer." (PMID 37187731, 2023).
periodontitis (7 papers, 2021 to 2025). An acute or chronic inflammatory process that affects the tissues that surround and support the teeth. "Previous studies have reported single-nucleotide polymorphisms (SNPs) of FCGR3A (rs396991 and rs4455090) were correlated with periodontitis and might impact susceptibility to periodontitis." (PMID 33777111, 2021). "FCGR3A (Fc fragment of IgG receptor IIIa) encodes a receptor for the Fc portion of immunoglobulin G, and FCGR3A polymorphisms are shown to confer susceptibility to periodontitis in Caucasians." (PMID 33869630, 2021). "We also identified three “master” immunosuppression genes, PECAM1, FCGR3A, and FOS, as candidate genes central to immune suppressive pathogenic mechanisms in periodontitis." (PMID 33777111, 2021). "Exploration of available transcriptomic datasets revealed C4A, C4B, CXCL12, FCGR3A, IL1B, and MMP3 as the top candidate molecular linkage genes between periodontitis and AD." (PMID 33869630, 2021). "Six genes C4A, C4B, CXCL12, FCGR3A, IL1B, and MMP3 were identified as the most significant crosstalk genes linking chronic periodontitis and Alzheimer's disease." (PMID 33869630, 2021). "Three “master” immunosuppression genes, PECAM1, FCGR3A, and FOS were identified as candidates pivotal to immunosuppressive mechanisms in periodontitis." (PMID 33777111, 2021). "PECAM1, FCGR3A, and FOS emerged as high-value biomarkers and candidate therapeutic targets for periodontitis." (PMID 33777111, 2021). "Among these 48 crosstalk genes and the chronic periodontitis-related genes in DisGeNET, C4A, C4B, CXCL12, FCGR3A, IL1B, and MMP3 were shared and identified as the most pivotal candidate links between periodontitis and AD." (PMID 33869630, 2021). "Besides, several studies have shown that both FCGR3A and MAPK pathway exhibited significant aberrant levels in some diseases such as chronic constriction and Periodontitis, while few studies have indicated the connection of FCGR3A and MAPK pathway." (PMID 35070236, 2022). "The central finding of our study is the identification of three distinct immunosuppression genes, PECAM1, FCGR3A, and FOS, which could be potentially high-value biomarkers or candidate therapeutic targets for periodontitis." (PMID 33777111, 2021).
leukemia (6 papers, 2019 to 2025). A malignant (clonal) hematologic disorder, involving hematopoietic stem cells and characterized by the presence of primitive or atypical myeloid or lymphoid cells in the bone marrow and the blood. "Finally, we detected the expression of marker genes of macrophage and NK cells, and found that five genes of FCAR, FCGR3A, PREX1, S100A8 and S100A9 all were significantly overexpressed in the leukemia cells of HAP1 compared with that in the normal stroma cells of HS-5 (p < 0.05)." (PMID 39583114, 2024).
Sepsis (6 papers, 2023 to 2025). Sepsis is defined as life-threatening organ dysfunction caused by a dysregulated host response to infection. "To validate the clinical significance of FCGR3A + macrophage-associated genes, we constructed a machine learning prediction model based on transcriptomic data from sepsis patients and identified 13 key genes." (PMID 41332909, 2025). "As a key receptor for immune regulation, FCGR3A is involved in both antibody-dependent cellular cytotoxicity and in modulating macrophage activation, further contributing to immune dysregulation in sepsis." (PMID 41332909, 2025). "FCGR3A+ monocytes, and CD14+ monocytes from the sepsis patients presented the highest PGK1 expression compared to the other patients and other cell types." (PMID 39712033, 2024). "Four proteins showed a >3-fold difference between HLH and sepsis: actin, cytoplasmic 1 (ACTB); actin, cytoplasmic 2 (ACTG1); CD16a antigen (FCGR3A); and plastin-2 (LCP1)." (PMID 37653176, 2023). "The upregulation of FcγR‐related genes, such as FCGR3A, FCGR1A, LYN, SYK, FYN and SRC, was detected in the prefrontal cortex, hippocampus, heart and colon of our sepsis patients, but not in the kidneys or lungs." (PMID 37731199, 2023).
Arthritis (5 papers, 2005 to 2023). Inflammation of a joint. "The association between arthritis and the FCGR2A and FCGR3A low copy number genotype has been identified in a cohort of Taiwan SLE patients." (PMID 26798662, 2015). "In particular, in the most recent study, the FCGR3A low copy number genotype was significantly enriched in SLE patients with arthritis (P = 0.001; OR = 1.56)." (PMID 26798662, 2015). "To explore the relationship between functional polymorphisms in FcγRs (FCGR3A-158V/F and FCGR2A-131H/R) and arthritis in individuals positive for anti-GPI antibodies, we evaluated these individuals with respect to FCGR genotype." (PMID 16277670, 2005).
gastric cancer (5 papers, 2014 to 2025). A primary or metastatic malignant neoplasm involving the stomach. "FCGR3A mRNA expression in gastric cancer (GC) was examined using TIMER and GEPIA databases." (PMID 39280892, 2022).
kidney transplant (5 papers, 2019 to 2025). A surgical procedure in which one or both kidneys from a donor are implanted into a recipient. "Taking together, these findings revealed that intragraft monocytes/macrophages with high FCGR3A expression play a critical role in kidney transplant rejections." (PMID 41030449, 2025). "In conclusion, our study highlights the substantial impact of genetic factors related to NK-cell functionality, specifically missing self, polymorphisms in KLRC2 rs9916629‐C/T, and, in DSA-positive patients, FCGR3A, on the risk of MVI occurrence in kidney transplant recipients." (PMID 39402708, 2025). "Taken together, our current data indicate that heterozygosity for FCGR3A may be unfavorable in kidney transplant recipients." (PMID 35632480, 2022).
Obesity (5 papers, 2021 to 2025). Accumulation of substantial excess body fat. "Specifically, we detected down-regulation of HLA-DRA (1.38-fold), STAT1 (1.3-fold), TNFSF10 (1.7-fold), and FCGR3A (fold reduction 1.65) with pregravid obesity." (PMID 34195568, 2021). "A study of the cellular composition of WAT in obesity revealed three populations of monocytes, including non-classical monocytes (FCGR3A, HES4) and classical monocytes: Mo-1 (FCER1A) and Mo-2 (CSF3R, FCAR, SELL)." (PMID 37569635, 2023).